IL4 (interleukin 4)
Diseases named in the same sentence as IL4 in open-access papers (continued):
Sharing a sentence is not in itself a finding about the gene and the disease.
scrub typhus (4 papers, 2011 to 2017). Scrub typhus is a rare dust mite-borne infectious disease caused by the Orientia tsutsugamushi bacterium and characterized clinically by an eruptive fever which is potentially serious. "Given that only two reports mentioned low IL-4 levels in serum samples of scrub typhus patients, our data presented here provide new insights into Th2 cytokines in inflamed tissues." (PMID 27479584, 2016). "Finally, while none of the healthy controls and only one of the 32 infectious disease controls had detectable IL-4 levels, 18 out of the 129 scrub typhus patients had measurable IL-4 levels." (PMID 24516677, 2014). "In contrast, IL-4 levels in people infected with Orientia tsutsugamushi (incitant of scrub typhus) and treated with tetracycline did not change relative to background levels." (PMID 21943280, 2011). "The cellular counts of IL-4-positive PBMCs upon antigen stimulation were not significantly different among the patient and control groups, demonstrating that Th1-biased cellular responses are dominant in scrub typhus patients." (PMID 29259327, 2017).
septic arthritis (4 papers, 2009 to 2021). "IL-4 deficient 129SV mice had a thousand times higher bacterial growth in their kidneys, significantly elevated mortality, and delayed development of septic arthritis." (PMID 33546401, 2021). "Septic arthritis mice pretreated with CTLA4-Ig exhibited more severe joint inflammation but lower levels of IL-4 compared to the control mice." (PMID 33546401, 2021). "Consistent with the inability of WT mice in controlling the infection, these mice showed Th2 profile in septic arthritis with high-IL-4/CD4+T cell and low-IFN-γ/CD4+T cell counts." (PMID 29867945, 2018). "This suggests that endogenous IL-33 is essential to driving type 2 response in septic arthritis which are mediated by IL-4." (PMID 29867945, 2018). "The aim of our study was to assess the role of IL-4 in our septic arthritis model, both regarding development of the arthritic process and host susceptibility to bacteria." (PMID 19606256, 2009). "Thus, to further address the mechanism underlying the outcome of ST2 deficiency in septic arthritis, it was next performed a flow cytometry gating CD4+IFN-γ+T cells and CD4+IL-4+T cells at the 7th and 14th day post-infection in LNs cells." (PMID 29867945, 2018).
severe combined immunodeficiency (4 papers, 2016 to 2024). Severe combined immunodeficiency (SCID) comprises a group of rare monogenic primary immunodeficiency disorders characterized by a lack of functional peripheral T lymphocytes resulting in early-onset severe respiratory infections and failure to thrive. "JAK3 knock-out mice are found to develop severe combined immunodeficiency (SCID) due to impairment in B cell development associated with IL-2, IL-4, IL-7, IL-9, and IL-15 receptor signaling." (PMID 38380328, 2024). "In this study, we report a 4-month-old boy with T−B+NK− severe combined immunodeficiency (SCID) due to a novel mutation in exon 2 of IL2RG, the gene encoding the interleukin (IL) common gamma chain (γc) of the cytokine receptors for IL-2, IL-4, IL-7, IL-9, IL-15, and IL-21." (PMID 35498802, 2022).
sporotrichosis (4 papers, 2019 to 2025). The commonest and least serious of the deep mycoses, characterized by nodular lesions of the cutaneous and subcutaneous tissues. "We herein described a previously unrecognized Th2 inclined response in circulation of patients with sporotrichosis caused by S. globosa: great increases in the percentage of Th2, the ratio of Th2/Tregs as well as IL-4 level in serum in whole patients." (PMID 33281813, 2020). "Here we observed IL-18 in sporotrichosis lesions was positively correlated with both local expression of IL-4 and IFN-γ." (PMID 40489556, 2025). "In the most severe cases of feline sporotrichosis, co-infection with FIV or FLV has been reported, which is known to cause feline immunosuppression with low CD4+/CD8+ ratio and decreased levels of IL-4 and IL-12 and high levels of the anti-inflammatory interleukin IL-10." (PMID 37233242, 2023). "In sporotrichosis cases, high levels of IL-4 have been found, which stimulate CD8 cell activation." (PMID 37233242, 2023). "Immunization with rSsEno plus PGA induced a predominantly T-helper 1 cytokine pattern after in vitro stimulation of splenic cells with rSsEno: elevated levels of IFN-γ and IL-2, as well as of other cytokines involved in host defense against sporotrichosis, such as TNF-alpha, IL-6, and IL-4." (PMID 31748544, 2019). "Cats coinfected with these viruses show some differences in cytokine levels, showing higher levels of IL-10 and lower levels of IL-4, IL-12, and CD4+/CD8+, compared to other cats with sporotrichosis without coinfection with these viruses." (PMID 37233242, 2023).
staphylococcus aureus infection (4 papers, 2009 to 2025). An infectious process in which the bacteria Staphylococcus aureus is present. "In the past, Th2 type cytokines IL-4 and IL-10 were associated with resistance to Staphylococcus infection in mice." (PMID 21857913, 2011). "The KEGG pathways associated with AD were mainly involved in the IL-10 signaling pathway, IL-4 and IL-13 signaling, TGF-beta receptor signaling, the TCR pathway during Staphylococcus aureus infection signaling, and the STAT3 pathways." (PMID 41471858, 2025).
thyroid tumor (4 papers, 2015 to 2024). A benign or malignant neoplasm affecting the thyroid gland. "However, the molecular mechanism underlying the role of IL-4 in thyroid tumors remains elusive." (PMID 38773979, 2024). "In CD95-resistant thyroid tumor cells, both PEA-15 and c-FLIP mRNA expressions are up-regulated through interleukin-4 (IL-4) and IL-1037." (PMID 34997083, 2022).
toxocariasis (4 papers, 2021 to 2025). A parasitic infection caused by worms found in domestic animals. "In contrast, in toxocariasis, Th2 cells are involved; they secrete IL-4, IL-5, IL-9, IL-10, and IL-13 and promote type 2 immunity, characterized by high antibody titers." (PMID 40943043, 2025).
Trichinella spiralis infection (4 papers, 2017 to 2024). "Furthermore, we show that robust induction of IL4 responses during Trichinella spiralis infection enhance the presence of nTh1 cells." (PMID 28406139, 2017). "Thus, invasive L. plantarum expressing FnBPA and IL-4 stimulates both mucosal and cellular immune response to protect against T. spiralis infection, highlighting its therapeutic potential as an effective DNA vaccine for trichinellosis." (PMID 35591986, 2022).
triple-negative breast carcinoma (4 papers, 2017 to 2024). An invasive breast carcinoma which is negative for expression of estrogen receptor (ER), progesterone receptor (PR), and human epidermal growth factor receptor 2 (HER2). "Here, we expand on those findings to determine mechanistically how IL4 signaling links glucose metabolism and histone acetylation to drive proliferation in the context of triple-negative breast cancer (TNBC)." (PMID 38731867, 2024). "The data presented here support a direct effect of IL4 signaling on triple-negative breast cancer mediated through the type II IL4 receptor." (PMID 38731867, 2024). "A statistically significant increase in the content of MCP-1, IL-1β, IL-2, IL-4, and IL-10 was found in triple-negative breast cancer." (PMID 36286034, 2022). "Together, this suggests that type II receptor signaling may affect the utilization of glucose to support IL4-induced histone acetylation and gene expression in triple-negative breast cancer." (PMID 38731867, 2024). "To assess these metabolic effects on triple-negative breast cancer in vitro, we treated two cell lines capable of spontaneous metastasis, human (MDA-MB-231) and murine (4T1) cell lines, with IL4 and quantified glucose uptake using the fluorescent glucose analog 2-NBDG." (PMID 38731867, 2024). "In contrast, no induction of IL-1β or IL-4 could be observed in the triple negative breast cancer cells (data not shown)." (PMID 28832545, 2017).
upper respiratory tract infection (4 papers, 2022 to 2024). "reduce IFNγ & TNF-α and increase IL-4 & IL-10 secretions to control the immunostimulatory effects in upper respiratory tract infection." (PMID 39294611, 2024).
vivax malaria (4 papers, 2019 to 2024). "Here, the increased frequency of cTfh2 (CXCR3-CCR6-) cells in acute vivax malaria might be induced by IL-4-producing T helper 2 (Th2) cells, as they have been shown to function in Tfh2 cell differentiation in other infection models." (PMID 39475899, 2024). "Patients with HBV monoinfection presented the same number of variables which concentrations were increased (mainly IFN-γ, TNF-α, IL-6 and CXCL9), when compared to asymptomatic vivax malaria monoinfection, but only significant decrease of one variable (also IL-4)." (PMID 31233500, 2019). "Hence, these antagonic tendencies suggests that different mechanisms, and not just the antimalarial response in this case, could be responsible for the elevation of IL-4 concentrations in coinfected and symptomatic vivax malaria patients." (PMID 31233500, 2019). "Asymptomatic vivax malaria patients presented a similar number of variables with significant concentrations increases (mainly IFN-γ, IL-10 and direct bilirubin) and decreases (such as CXCL10, IL-1β, IL-4 and indirect bilirubin)." (PMID 31233500, 2019). "Although IL-4 levels could not distinguish coinfected and symptomatic vivax malaria patients, correlations with IL-4 concentrations were completely different in both study groups." (PMID 31233500, 2019).
acute liver failure (3 papers, 2006 to 2022). Rapid deterioration of liver function causing encephalopathy and coagulopathy. "Similarly, several reports show an increased level of cytokines, such as IFN-Ɣ IL-1β, IL-12, IL-4, and IL-10 with ongoing AHE infection and HEV-associated acute liver failure." (PMID 34335528, 2021). "Elevated serum levels of several cytokines, including TNF-α, sTNF-αR1, sTNF-αR2, IL-2, IL-2R, IL-4, IL-6, IL-8, IL-10, and interferon-γ, have been described in patients with ACLF, whereas other studies reported normal TNF-α levels in patients with ACLF or acute liver failure." (PMID 17156425, 2006).
adenomyosis (3 papers, 2020 to 2025). The growth of endometrial tissue inside the muscular wall of the uterine corpus. "In external adenomyosis, the analysis predicted the activation of multiple upstream regulators such as LPS, TGFB1, IL4, and IFNG." (PMID 40531845, 2025). "Upstream regulator analysis predicted the activation of inflammatory mediators like LPS, TGF-β1, IL-4, and IFN-γ in external adenomyosis, and MAPK1 and IRF2BP2 along with multiple microRNAs in internal adenomyosis." (PMID 40531845, 2025). "Therefore, STAT3, VIM, VEGFA and HSP90B1 that were also annotated in interleukin-4 and interleukin-13 signalling in the present GSEA need to be validated to verify potential downregulation of this pathway in women with adenomyosis." (PMID 32933042, 2020).
allergic bronchopulmonary aspergillosis (3 papers, 2011 to 2024). Allergic bronchopulmonary aspergillosis (ABPA) is a rare immunologic pulmonary disorder caused by hypersensitivity to Aspergillus fumigatus, clinically manifesting with poorly controlled asthma and recurrent pulmonary infiltrates. "For example, allergic bronchopulmonary aspergillosis (ABPA) is characterized by Th2 and Th9 cell-type immunity and involves interleukin (IL)-4, IL-5, IL-13, and IL-10." (PMID 38667922, 2024). "This “by-stander” effect was demonstrated by Moss who found an IL-4-dependent elevation of nonspecific IgE was induced by A. fumigatus in an allergic bronchopulmonary aspergillosis mouse model." (PMID 21785589, 2011).
amebiasis (3 papers, 2015 to 2017). A parasitic infectious disorder caused by amoebas. "In order to describe the immune response induced by IL-25 during amebiasis, we measured IL-4, IL-5, and IL-9 by enzyme-linked immunosorbent assay (ELISA) from cecal tissue lysates of mice after E. histolytica challenge with or without rIL-25 treatment." (PMID 28246365, 2017). "In fact, IFN-γ production by peripheral mononuclear cells was shown to be correlated with protection from future E. histolytica infection in children and the serum level of IL-4 was high in patients with invasive amebiasis." (PMID 27242782, 2016).
ankylosing spondylitis (3 papers, 2015 to 2025). An autoimmune chronic inflammatory disorder characterized by inflammation in the vertebral joints of the spine and sacroiliac joints. "IL-17 mRNA expression levels were increased in patients with myiasis and ankylosing spondylitis, and IL-4 in patients with vasculitis and unknown skin infection." (PMID 27379100, 2016). "Furthermore, the percentage of Th17 cells and expression level of IL-17A were found to be significantly higher in ankylosing spondylitis patients, while the protein levels of IL-4 and TGF-β were unchanged." (PMID 25452811, 2015). "In the present study, the protein levels of IL-4 and TGF-β were found to be unchanged in ankylosing spondylitis patients (mild and severe) compared with the control group, which is in accordance with a previous study." (PMID 25452811, 2015). "In addition, the mRNA expression levels of IL-4 and TGF-β were found to be higher in punctured cells of the mild and severe ankylosing spondylitis groups." (PMID 25452811, 2015). "Therefore, IL-4 and TGF-β may not participate in the progression of ankylosing spondylitis." (PMID 25452811, 2015).
aortic aneurysm (3 papers, 2013 to 2022). A ruptured aneurysm located in the wall of the proximal portion of the descending aorta proceeding from the arch of the aorta. "In contrast, other groups have found that CD4+ T cells in aortic aneurysms are predominantly IL-4-producing Th2 cells." (PMID 35463756, 2022). "The mRNA expressions of IFN-γ, IL-4 and IL-10 were significantly increased in the aortic aneurysms of Ang II-treated group compared with saline-treated controls." (PMID 24358274, 2013). "For example IL-4, a cytokine classically produced by Th2 cells, has been proposed as protective in ATH, but IL-4 also increases the expression of P-selectin, VCAM-1, and matrix metalloprotease 1 and 12, which are implicated in aortic aneurysm formation and in acute coronary syndrome." (PMID 23533763, 2013).
aplastic anemia (3 papers, 2014 to 2025). Anemia resulting from bone marrow failure (aplastic or hypoplastic bone marrow). "One group investigated the efficacy of arsenic trioxide on the T-regulatory cell ratio and the levels of IFN-γ, IL-4, IL-17, and TGF-β1 in the peripheral blood of patients with severe aplastic anemia." (PMID 39851523, 2025).
ascariasis (3 papers, 2021 to 2025). An infection that is caused by the roundworm Ascaris lumbricoides, many cases of which remain asymptomatic. "It was found that, in mothers with ascariasis, there is an in utero sensitization of newborns to Ascaris lumbricoides, with a greater frequency of CD4+ T cells producing IFN-γ and IL-4 in CB from newborns of infected mothers, showing that the immunological effects of infection develop in the fetus." (PMID 33668787, 2021). "For schistosomiasis, but not ascariasis, six months after anti-helminthic treatment, the CD4+ T cell immune phenotype demonstrated an increase percentage of IL-4 producing and decreased percentage of TNF and IFN-γ producing antigen-specific CD4+ T cells compared to uninfected controls." (PMID 33668787, 2021).
Ataxia (3 papers, 2011 to 2022). Ataxia refers to impaired coordination of voluntary muscle movement. "Although IL-4 did not contribute to hypothermia or ataxia (not shown) following LT challenge, it remained possible that this cytokine still affected resistance to spore challenge." (PMID 22241984, 2011). "Lukens’ study shows that the absence of NLRP12 promoted IL-4 secretion resulting in the development of atypical EAE disease symptoms, including ataxia and impaired balance control." (PMID 29403486, 2017).
bacterial pneumonia (3 papers, 2020 to 2024). Acute infection of the lung parenchyma caused by bacteria (e.g., Streptococcus pneumoniae, Haemophilus influenzae, Chlamydia pneumoniae, Mycoplasma pneumoniae, and Legionella pneumophila). "Cytokines IL-4 and IL-13 in lung are shown to play important roles in driving M2 polarization of alveolar macrophages (AMs), which could result in the susceptibility of mice to bacterial pneumonia." (PMID 32200357, 2020). "Patients with bacterial pneumonia exhibited the greatest elevation and number of cytokines in urine that differed from healthy controls; S. aureus pneumonia patients differed in all 11 cytokines with IL-4, IL-15, Gro-α, MIP-1α and SDF-1 uniquely elevated in those patients." (PMID 32770049, 2020).
Barrett esophagus (3 papers, 2020 to 2024). Esophageal lesion lined with columnar metaplastic epithelium which is flat or villiform. "In the so-called Barrett’s esophagus an acute inflammatory state (esophagitis) evolves towards a state of chronic inflammation characterized by presence of IL-4 and IL-13, suppressive M2 macrophages and MDSCs." (PMID 38638445, 2024). "We further examined the effect of IL-33 on tumor-related cytokines and found that the mRNA expressions of IL-4 and IL-6 were significantly higher in the esophageal adenocarcinoma cells after IL-33 stimulation." (PMID 36110250, 2022). "We detected the tissue mRNA expression of IL-1β, IL-4, IL-6, and IL-10 in the esophageal adenocarcinoma rat model." (PMID 36110250, 2022).
brain cancer (3 papers, 2018 to 2020). A primary or metastatic malignant neoplasm affecting the brain. "Our results showed that PG2 alone or in combination with GM-CSF+IL4 also enhanced the production of functional mDCs in the breast, colon, ovarian, liver, gastric, and brain cancers." (PMID 31547048, 2019).
cardiac arrest (3 papers, 2015 to 2021). Cessation of breathing and/or cardiac function. "IL-4, IL-12p70, and TNFα were expressed at significantly different levels between skin and muscle tissues within the “cardiac arrest group” animals." (PMID 26635801, 2015). "TNFα and IL-4 were identified as important cytokines in both “cardiac arrest group” skin and muscle and are known to play a role in many immune regulation or intercellular signaling contexts." (PMID 26635801, 2015). "Cardiac arrest and ECPR markedly increased the plasma levels of IL-10, VEGF, leptin, TNF-α, IL-1β, IL-6, fractalkine, IL-5, IL-18, IP-10, IL-4, eotaxin, MIP-1α, IL-17α, IL-12, RANTES, G-CSF, LIX, and MCP-1." (PMID 34781966, 2021).
cholangitis (3 papers, 2016 to 2025). An acute or chronic inflammatory process affecting the biliary tract. "Zen research showed that the expression of Th2 cytokines (IL-4, IL-5, and IL-13) and regulatory cytokines (IL-10 and transforming growth factor-β) was upregulated in the lesion tissues of patients with IgG4-related sclerosing pancreatitis and cholangitis." (PMID 38669380, 2024). "Hence, administration of IL-4 activates CD8+ T, NK and NKT cells to secrete more IFN-γ and exacerbate cholangitis." (PMID 27721424, 2016).
choroidal neovascularization (3 papers, 2020 to 2024). An eye disorder described by the growth of new blood vessels that originate from the choroid through a break in the Bruch membrane into the sub–retinal pigment epithelium (sub-RPE) or subretinal space. "Herpud1, upregulated in IL-4-treated macrophage, promoted their migration, and, in a mouse model of choroidal neovascularization (CNV), it promoted M2 macrophage polarization, favoring the development of CNV." (PMID 39453673, 2024). "Requirements of IL-4/IL-4Rα in the inductive phase of choroidal neovascularization (CNV)." (PMID 32366355, 2020). "(a) Requirement of IL-4 in bone marrow for choroidal neovascularization (CNV)." (PMID 32366355, 2020).